ABHD14A (abhydrolase domain containing 14A)
Description:
Possible role in granule neuron development.
Synonyms: DKFZP564O243; DORZ1
Tractability: Antibody: UniProt predicts a signal peptide or a membrane-spanning region. PROTAC: ubiquitination databases record sites on it.
Gene: Protein-coding gene on chromosome 3 (51,971,426 to 51,981,197, forward strand). Ensembl gene ENSG00000248487.
Subcellular location: Cytoplasm; Membrane
Subcellular location (Human Protein Atlas): Vesicles
Gene Ontology:
Cellular component: cytoplasm; membrane
Genetic constraint (gnomAD): Loss-of-function variants: 19 observed, 25.79 expected, observed/expected ratio (o/e) 0.74, 90% interval 0.51 to 1.08. The upper end of that interval is the gene's LOEUF score, 1.08, which puts it in group 4 of 6, group 1 being the genes least tolerant of losing a copy. Missense variants: 311 observed, 333.73 expected, observed/expected ratio (o/e) 0.93, 90% interval 0.85 to 1.02. Synonymous variants: 148 observed, 155.23 expected, observed/expected ratio (o/e) 0.95, 90% interval 0.83 to 1.09.
Homologues: Orthologues: chimpanzee ABHD14A (98% identical), pig ABHD14A (85% identical), guinea pig ABHD14A (79% identical), mouse Abhd14a (74% identical), rat Abhd14a (74% identical), zebrafish abhd14a (46% identical), tropical clawed frog abhd14a (39% identical), Caenorhabditis elegans C31H5.1 (15% identical), Caenorhabditis elegans F10D2.10 (14% identical), Caenorhabditis elegans F35H12.5 (14% identical), Caenorhabditis elegans Y73C8B.3 (13% identical), Caenorhabditis elegans Y73C8B.1 (13% identical), and 8 more. Paralogues in human: ABHD14B (33% identical), MEST (20% identical), ABHD11 (20% identical), EPHX2 (20% identical), EPHX4 (19% identical), BPHL (18% identical), ABHD5 (17% identical), ABHD6 (17% identical), EPHX3 (16% identical), ABHD4 (15% identical), ABHD8 (15% identical), SERHL2 (13% identical).
Diseases named in the same sentence as ABHD14A in open-access papers:
ABHD14A is named in the same sentence as 6 diseases in open-access papers, as found by Europe PMC text mining. Sharing a sentence is not in itself a finding about the gene and the disease. The quoted sentences say what the papers report.
breast carcinoma (1 paper, 2020). "There was only one report of ABHD14A in cancer where it was downregulated in breast cancer with visceral organ metastasis; however, the ABHD14A and TMEM132E AS events were not fully explored." (PMID 33142748, 2020).
degenerative joint disease (1 paper, 2019). "ABHD14A may be involved in the development of granule neurons, while IPO8 is involved in a common bone marrow mesenchymal stem cell degenerative joint disease." (PMID 31756171, 2019).
metabolic disorders (1 paper, 2022). "ABHD14A is associated with metabolic disorders of biological oxidation enzymes, and ADSSL1 with Purine ribonucleoside monophosphate biosynthesis." (PMID 35027621, 2022).
ABHD14A also shares sentences with these, for which no sentence is quoted: cancer (1 paper); metastatic disease (1); tumours (1).